TRAF3 (TNF receptor associated factor 3)
Diseases named in the same sentence as TRAF3 in open-access papers (continued):
Sharing a sentence is not in itself a finding about the gene and the disease.
Autoimmunity (12 papers, 2018 to 2025). The occurrence of an immune reaction against the organism's own cells or tissues. "On the other hand, enhanced CD40 signaling through TRAF3 mutations led to autoimmunity and increased risk of B-cell malignancy in humans, while a lack of CD40 signaling through CD40L mutations led to immunodeficiency in humans." (PMID 40473841, 2025). "Other TRAF3 variants have recently been described as causes of TRAF3-haploinsufficiency - a phenotype of recurrent bacterial infections, autoimmunity, systemic inflammation, B cell lymphoproliferation and hypergammaglobulinemia." (PMID 40455168, 2025). "The clinical phenotype of patients with TRAF3 haploinsufficiency (TRAF3HI) is marked by autoimmunity, immunodeficiency, and a predisposition to B cell malignancies, all of which are reminiscent of the immune cell-specific TRAF3 deficient mouse models." (PMID 36814922, 2023). "This phenotype suggests that TRAF3 over-expression also causes excessive B-cell function that can manifest as SLE-like autoimmunity, in this case perhaps by driving B cell differentiation to produce abundant antibody-secreting cells (ASCs) via a process that might speculatively be PRR-dependent." (PMID 30687320, 2018). "Csk H21I and K43D will be useful tools for dissecting the protein-specific drivers of autoimmunity mediated by the human polymorphism PTPN22 R620W, which impairs interaction with Csk and with the E3 ubiquitin ligase TRAF3." (PMID 35393453, 2022). "TRAF3 transgenic mice with overexpressed TRAF3 showed improved humoral responses, resulted in a series of symptoms including plasmacytosis, autoimmunity, inflammation and cancer." (PMID 32579175, 2020). "Consistent with the role of some of these antibodies in autoimmunity, TRAF3/BCL2 double-tg mice also develop autoimmune lesions, such as IgG depositions in glomeruli and tertiary lymphoid organs formation." (PMID 30687320, 2018). "Previous studies have shown that TRAF3 degradation promotes microglia-mediated CNS inflammation, and TRAF3 haploinsufficiency syndrome exhibits B cell hyperactivity leading to hypergammaglobulinemia and autoimmunity." (PMID 40577117, 2025). "Interestingly, transgenic overexpression of TRAF3 in B cells also renders B cells exhibiting enhanced reactions (also termed hyperreaction) to antigens and TLRs, resulting in autoimmunity and chronic inflammation." (PMID 36776285, 2023). "The presence of clones expressing autoreactive Ig, such as anti-nuclear antibodies (ANAs) is also consistent with the involvement of TRAF3 in the development of autoimmune disorders and confirms previous results showing the existence of ANAs in the serum of the TRAF3-tg mice." (PMID 30687320, 2018). "One of the consequences of TRAF3 deficiency (presumably attributed to the NF-kB2 over-activation) is the expansion of marginal zone (MZ) B cells, which might explain the hyperreactivity to TLR ligands and the systemic lupus erythematosus (SLE)-like autoimmunity observed in these mice." (PMID 30687320, 2018). "TRAF3 suppresses the development of experimental autoimmune encephalomyelitis (EAE) and IL-17 mediated EAE in part by its role as a negative regulator of the IL-17 induced inflammation and autoimmunity." (PMID 31316496, 2019). "In contrast, lymphocyte-specific TRAF3-tg mice develop progressive plasmacytosis and hypergammaglobulinemia, show exacerbated TLR responses as well as increased IgG production in response to T-I and T-D antigens, and develop systemic inflammation and SLE-like autoimmunity." (PMID 30687320, 2018).
herpes simplex encephalitis (12 papers, 2017 to 2025). Herpes simplex virus encephalitis (HSE) is caused by the infection of the central nervous system by Herpes simplex virus (HSV) that could have a devastating clinical course and a potentially fatal outcome particularly with delay or lack of treatment. "The TRAF3 Arg118Trp variant, for example, was initially associated with herpes simplex encephalitis, and TRAF3 deficiency is therefore linked to herpes infections in major reference resources (OMIM 614849)." (PMID 40455168, 2025). "AD TRAF3 deficiency was first reported in 2010 in a patient with herpes simplex virus encephalitis (HSE) heterozygous for the p.R118W TRAF3 variant, which is located within the zinc-finger domain." (PMID 41608125, 2025). "Gene mutations in nucleic acid sensing components such as TLR3 or its downstream signaling molecules (including UNC93B1, TLR3, TRIF, TRAF3, TBK1, IRF3, etc.)are one of the causes of herpes simplex encephalitis." (PMID 38814453, 2024). "The R118W mutation of TRAF3 is also found in herpes simplex encephalitis (HSE) patients." (PMID 36845015, 2023). "Variants in TLR3 as well as TRIF, TRAF3, TBK1, IRF3, and NEMO that code for mediators downstream of TLR3, and UNC93B1 that is involved in TLR3 trafficking, all reduce type I interferon signaling and are reported genetic causes of herpes simplex encephalitis (HSE)." (PMID 35126383, 2021). "Additionally, some fatal cases of herpes simplex encephalitis (HSE) are associated with defects in key genes in the interferon signaling pathway, such as TRIF, TBK-1, TLR3, and TRAF3." (PMID 40285022, 2025).
Obesity (9 papers, 2016 to 2025). Accumulation of substantial excess body fat. "In mouse models of high fat diet-induced and genetic obesity, hepatocyte-specific TRAF3 deficiency decreases insulin resistance, hepatic steatosis, and expression of pro-inflammatory cytokines in the liver, while development of obesity per se is not altered." (PMID 35252400, 2022). "CircARF3 is linked to obesity-induced inflammation in mouse adipose tissues where it functions as a miR-103 sponge and accelerates inflammation by regulating TNF receptor-associated factor 3 (TRAF3) expression." (PMID 34561612, 2021). "The role of B cell TRAF3 deficiency in the context of obesity is an intriguing avenue of future research." (PMID 27752131, 2016). "Collectively, the observations in TRAF3-LKO mice suggest that HFD-induced obesity, insulin resistance and glucose metabolic disturbance are inhibited by a liver-specific deficiency of TRAF3." (PMID 26882989, 2016). "Our findings strongly demonstrate that siglec-E plays an adaptative role in protecting the adipocytes from inflammatory-mediated injury through reduced immune cell recruitment and TRAF3/Akt2 activity in AT during the early phase of obesity progression." (PMID 39967660, 2025). "Taken together, these findings suggest that siglec-E plays a crucial role in obesity-induced inflammation by controlling the expression of TRAF3 and Akt2 in the AT." (PMID 39967660, 2025). "During obesity, TRAF3 switches into a pro-inflammatory phenotype that exacerbates metabolic dysfunction and insulin resistance." (PMID 39967660, 2025). "Recent work has shown significant improvements in obesity, insulin resistance, liver steatosis and inflammatory responses in liver-specific TRAF3 knockout mice." (PMID 35937592, 2022). "On the contrary, another study reported that myeloid cell TRAF3 promotes metabolic inflammation, insulin resistance, and hepatic steatosis in obesity." (PMID 32560220, 2020). "In several mouse models of obesity, genetic deletion of Traf3 in macrophages and neutrophils alleviates a number of hallmarks of obesity-related inflammation." (PMID 30319624, 2018). "Next, four liver-specific TRAF3-transgenic (TRAF3-LTG) mouse lines were created to further validate the regulatory function of hepatocyte TRAF3 in hepatic steatosis-related obesity and insulin resistance." (PMID 26882989, 2016). "More importantly, this TAK1 inhibitor largely abolished the exacerbation of obesity and insulin resistance that was observed in mice with liver-specific TRAF3 overexpression." (PMID 26882989, 2016). "Our results suggest that the deletion of siglec-E might contribute to obesity-related inflammation by actively inducing the expression of TRAF3 in the AT." (PMID 39967660, 2025). "Conversely, transgenic mice that overexpress TRAF3 in liver cells showed increased obesity." (PMID 35937592, 2022). "After 24 weeks on a high-fat diet (HFD), obesity, insulin resistance, hepatic steatosis and inflammatory responses are significantly ameliorated in liver-specific TRAF3-knockout mice, but exacerbated in transgenic mice overexpressing TRAF3 in hepatocytes." (PMID 26882989, 2016). "Thus, based on the combined results from the gain- and loss-of-function approaches in vivo and in vitro, we concluded that the upregulated TRAF3 expression in hepatocytes functions as a positive regulator of HFD-induced obesity and insulin resistance." (PMID 26882989, 2016). "However, it remains unclear whether TRAF3 and TLR4 signaling is associated with siglec-E that alters AT microenvironment to mediate obesity and AT inflammation." (PMID 39967660, 2025). "These authors further showed that myeloid TRAF3 may have anti-inflammatory and proinflammatory activities in lean and obese mice respectively, suggesting that, in obesity progression, myeloid TRAF3 functionally switches its activity from anti-inflammatory to proinflammatory modes." (PMID 32560220, 2020).
Obesity (continued). "In obesity, key molecules in NIK signaling pathway such as BAFF, CD40L, TRAF2, TRAF3, NIK, and p52 are abnormally elevated." (PMID 35807520, 2022). "Although plasma cytokines such as BAFF and CD40L are significantly elevated in obesity, TRAF2 and TRAF3 are still highly expressed in the obese liver, which is likely due to the activation of their transcription." (PMID 35807520, 2022). "After further HFD treatment for 4 weeks, although HFD-induced obesity was not significantly influenced by TRAF3 upregulation, mice with AdTRAF3 injection clearly exhibited increased fasting glucose and insulin levels but decreased insulin sensitivity and glucose tolerance." (PMID 26882989, 2016).
autoimmune disease (8 papers, 2014 to 2025). A disorder resulting from loss of function or tissue destruction of an organ or multiple organs, arising from humoral or cellular immune responses of the individual to their own tissue constituents. "Humans with a mutant TRAF3 allele have autoimmune disease, immunodeficiencies, and increased risk of B cell malignancies." (PMID 40773231, 2025). "The deficiency of TRAF3 also induces B cell hyperactivation by enhancing mitochondrial respiration, thereby increasing the risk of autoimmune diseases." (PMID 37680644, 2023). "TRAF3 deficiency induces the overactivation of B cells by intrinsically activating multiple pro-inflammatory pathways which increases the risk of autoimmune disorders." (PMID 37680644, 2023). "For example, humans with TRAF3 haploinsufficiency -like B-Traf3−/− mice- exhibit increased incidence of B cell–driven autoimmune diseases and BCLs." (PMID 40773231, 2025). "However, increased expression of CD40 ligand (CD154) leading to more CD40 activation is associated with autoimmune diseases including SLE and Sjögren’s disease, both of which also affect patients with TRAF3 haploinsufficiency (12, 36, –38)." (PMID 40773231, 2025). "Targeted treatment of TRAF3 or TLR is beneficial to treating autoimmune diseases or conditions." (PMID 36845015, 2023). "Our study sheds light on the mechanism of specificity and diversity achievement in the complicated regulation of TRAF3 activity, suggesting that HSCARG is a potential target for the treatment of inflammatory and autoimmune diseases." (PMID 24763515, 2014). "TRAF3 is part of other annotated pathways, such as NOD-like receptor signaling, RIG-I-like receptor signaling, IL-17 signaling, and TNF signaling, all known to be altered in autoimmune diseases and MS development (35, –37)." (PMID 40577117, 2025). "Here we demonstrated that HSCARG plays an important role in the precise control of the cellular antiviral response by negatively regulating TRAF3 ubiquitination and IFN-β production, providing a potential target for the treatment of chronic inflammation and autoimmune disease." (PMID 24763515, 2014).
diffuse large B-cell lymphoma (8 papers, 2018 to 2025). "Consistent with a previous study, we found that TRAF3 co-immunoprecipitated with GSK3β in three BCL cell lines: BJAB, a Burkitt Lymphoma; Karpas 422, a Germinal Center B cell-like Diffuse Large B Cell Lymphoma (GCB DLBCL), and Dawo, a DLBCL not otherwise specified." (PMID 36291813, 2022).
colitis (7 papers, 2018 to 2024). Inflammation of the colon. "NLRP12-deficient mice, a mouse model with functional relevance to TRAF3, is highly susceptible to colitis and colitis-associated colon cancer." (PMID 34257589, 2021). "Lamc2 and Traf3 are usually overexpressed in the colitis, and both of them would further aggravate inflammation." (PMID 35565775, 2022). "Additional studies found that myeloid cell-specific knockout of TRAF2 or TRAF3 aggravated colitis by promoting expression of pro-inflammatory cytokines stimulated by TLRs in macrophages." (PMID 34956195, 2021). "TRAF3 also acts as a colitis regulator by binding with the IL-17 receptor and interfering with the IL-17-mediated proinflammatory pathway in mice with TNBS-induced colitis." (PMID 32848509, 2020). "DSS-induced colitis models of TRAF2- and TRAF3-deficient mice reveal similar functions of TRAF2 and TRAF3 as negative regulators of experimental colitis by decreasing proinflammatory cytokines and reducing the infiltration of immune cells in the colon." (PMID 32848509, 2020). "Similar to M-TRAF2−/− mice, young adult M-TRAF3−/− mice exhibit exacerbated DSS-induced colitis with increased levels of inflammatory cytokines produced by TRAF3−/− macrophages in response to TLR signaling." (PMID 30294322, 2018). "In addition, TRAF3 has been shown to be a negative regulator of inflammation in the TNBS-induced colitis mouse model by interfering with IL-17/IL-17R/Act1/TRAF6-mediated proinflammatory pathways though binding to IL-17R." (PMID 34956195, 2021). "Notably, another mouse model with functional relevance to TRAF3, NLRP12−/− mice, is highly susceptible to colitis and colitis-associated colon cancer." (PMID 30294322, 2018). "Indeed, the blockade of DUBA-mediated deubiquitination of TRAF3 by DUBA-specific siRNA cancelled the negative regulatory effects of NOD2 on DSS-induced colitis in mice treated with CpG, and mice treated with DUBA-siRNA displayed severe DSS-induced colitis even after repeated MDP injections." (PMID 39403381, 2024). "Myeloid cell-specific deletion of TRAF3 does not affect macrophage differentiation, but renders mice hypersensitive to colitis induction in the dextran sodium sulfate (DSS) model." (PMID 30140268, 2018). "Like TRAF3, TRAF2 negatively regulate induction of proinflammatory cytokines by the TLR ligands LPS and polyIC as well as by the cytokine IL-1β, and the myeloid cell-conditional TRAF2 knockout (TRAF2-MKO) mice are hypersensitive to colitis induction in the DSS model." (PMID 30140268, 2018).
COVID-19 (7 papers, 2020 to 2026). A disease caused by infection with severe acute respiratory syndrome coronavirus 2. "Coronavirus disease-COVID-19 and lipid and atherosclerosis connect with TRAF3, TLR2, SELP and CASP1 deregulated molecules." (PMID 36553678, 2022).
diabetes (7 papers, 2011 to 2025). "Furthermore, β cells can promote macrophage activation and recruitment in a TNF-receptor-associated factor 3 (TRAF3)-dependent manner through miR-29 exosomes and the expression of miR-29, accelerating the onset of diabetes and inflammation." (PMID 41158622, 2025). "Traf3 is a target of microRNA-322; in a mouse model of diabetes, maternal disease and high glucose decreases microRNA while Traf3 expression and caspase-mediated apoptosis of neural stem cells is increased." (PMID 30319624, 2018). "Expression of miRNA-29 in pancreatic β cells promotes inflammation and diabetes via TRAF3." (PMID 37359091, 2023). "Animal and clinical evidence indicates that the function and expression of TRAF3 are involved in the pathogenesis of a variety of inflammation-related diseases, such as inflammatory bowel disease, liver inflammation, diabetes, bone inflammation, encephalitis, and autoimmune inflammation." (PMID 35116066, 2022). "In addition, a recent study showed that miR-29 is involved in inflammation and diabetes mellitus through the downregulation of TRAF3." (PMID 36140215, 2022). "In the liver, TRAF3 contributes to hepatic cell death following ischemia/reperfusion injury and to hepatic steatosis following HFD (high-fat diet)-induced diabetes, in part, through promotion of via TAK1-MKK-JNK signaling." (PMID 34440839, 2021). "Given the critical role of TLR4/TRAF3 in regulating the immune response, it is conceivable that MLGZG might exhibit improved therapeutic efficacy in treating other metabolic diseases, such as diabetes." (PMID 35116066, 2022).
head and neck squamous cell carcinoma (7 papers, 2019 to 2025). A squamous cell carcinoma that arises from any of the following anatomic sites: lip and oral cavity, nasal cavity, paranasal sinuses, pharynx, larynx, and salivary glands. "Most notably, the human papilloma virus-positive (HPV+) head and neck squamous cell carcinomas (HNSCC) exhibit an exceptionally high frequency (~20%) of deep deletions and truncations of the TRAF3 gene." (PMID 34745083, 2021). "Defects in TRAF3/CYLD have been implicated in the activation of NF-κB signaling in HPV-positive head and neck squamous cell carcinoma (HNSCC) and EBV-positive NPC26,37, suggesting that TRAF3 and CYLD genetic alterations may also participate in EBV-mediated tumorigenesis in pulmonary LELC." (PMID 31311932, 2019). "Interestingly, the human papilloma virus (HPV) positive head and neck squamous cell carcinoma (HNSCC) tumors have much higher frequency (~ 22%) of deep deletions and truncations of TRAF3, compared to the HPV negative HNSCC tumors." (PMID 32514408, 2020).
influenza (7 papers, 2020 to 2025). An acute viral infection of the respiratory tract, occurring in isolated cases, in epidemics, or in pandemics; it is caused by serologically different strains of viruses (influenzaviruses) designated A, B, and C, has a 3-day incubation period, and usually lasts for 3 to 10 days. "For instance, TRIM35 mediates the protection against influenza infection by activating TRAF3 and inducing K48-linked ubiquitination and degradation of PB2." (PMID 38498560, 2024). "Moreover, we clarified that inhibiting ubiquitinated degradation of TRAF3 was associated with anti-influenza effect, thereby facilitating antiviral immunity upon influenza A virus infection." (PMID 35573779, 2022). "Based on the significant effect of TRAF3 on anti-influenza virus infection and type I IFN signaling pathway, we further explored the anti-influenza virus effect of each domain of TRAF3 by constructing mutants with deletion of each domain." (PMID 35573779, 2022). "The TRAF3-WT group significantly reduced the expression of influenza PB2 and NP proteins compared with the vector group, which was consistent with the previous results." (PMID 35573779, 2022). "We further demonstrated the key domains of TRAF3 involved in anti-influenza effect." (PMID 35573779, 2022). "The results demonstrated that the number of plaque formations and viral PA mRNA expression levels in the TRAF3 knockdown group were significantly higher than those in the NC group, indicating that TRAF3 knockdown would increase the production of influenza progeny virions." (PMID 35573779, 2022).